EGFR (epidermal growth factor receptor)
Diseases named in the same sentence as EGFR in open-access papers (continued):
Sharing a sentence is not in itself a finding about the gene and the disease.
skin toxicity (43 papers, 2011 to 2026). "In patients treated with erlotinib, a lower serum level of IL-8, leading to stronger EGFR inhibition, was associated with a higher grade of skin toxicity." (PMID 36269747, 2022). "In conclusion, PZH Unguentum Compositum provides an additional option for the patients suffering from skin toxicity caused by EGFR-TKIs." (PMID 36165327, 2022). "At the basic research phase of SCCHN, an EGFR-R521K genotype (G/G) was reportedly associated with increased Cmab-induced skin toxicity." (PMID 30619755, 2018). "The frequency and severity of skin toxicity associated with nimotuzumab appears to be lower than that associated with other anti-EGFR antibodies." (PMID 25185971, 2015). "As panitumumab treatment has an increased risk of skin toxicity, a common adverse event with anti-EGFR agents, we also sought to assess the correlation between HRQoL and severity of skin toxicity." (PMID 21989186, 2011). "In patients treated with various EGFR inhibitors, including gefitinib, erlotinib, cetuximab, and panitumumab, low levels of serum IL-8 correlating with stronger EGFR inhibition were also associated with a higher grade of skin toxicity." (PMID 36269747, 2022). "But not only mutations in the EGFR itself seem to be associated with skin toxicity." (PMID 34012511, 2021). "We hypothesize that this SNP leads to decreased activity of RPS7 and thereby decreased follicular proliferation, thereby leading to lower susceptibility to EGFR inhibitor-induced skin toxicity." (PMID 30557370, 2018). "A retrospective exploration of several trials done with panitumumab, another anti-EGFR monoclonal antibody, confirmed an association between clinically graded skin toxicity and patient-reported outcome, quality of life, longer progression-free survival and overall survival." (PMID 23855804, 2013). "Present results also show a tendency for an association between intron 1 EGFR polymorphism and cetuximab-related skin toxicity: the incidence of grade 2-3 toxicity was 1.5-fold greater in patients bearing short CA-repeats in intron 1 of EGFR gene (CA sum ≤ 35) as compared to others (p = 0.058)." (PMID 22117530, 2011). "Moreover, in case of an expected high risk for severe skin toxicity one might choose to start prophylactic therapy such as a tetracycline derivative, since it is well known that EGFR inhibitor-induced skin toxicity negatively influences quality of life." (PMID 30557370, 2018). "It is reported that around 80% of patients receiving anti-EGFR mAbs treatment develop skin toxicity, with approximately 10% of cases classified as grade 3-4 toxicity." (PMID 41049433, 2025). "Although anti-EGFR inhibitors have a remarkable survival rate for mCRC patients with wild-type RAS, the associated skin toxicity and physical and mental image change negatively impact the quality of life." (PMID 36980549, 2023). "The severity of EGFR inhibitor-induced skin toxicity is positively correlated with the therapeutic effect, making related skin toxicity a potential marker for predicting drug efficacy." (PMID 35223483, 2022). "At 50 mg/m2 and at all lower doses, anti-EGFR ILs-dox were well tolerated; grade 1 skin toxicity occurred in two patients, and only 22 serious adverse events were observed in 17 patients, mostly due to tumor progression." (PMID 34998092, 2022). "The survey captured real-world data on current practices and opinions of mCRC patients for managing anti-EGFR skin toxicity and utilized the DLQI, a validated measurement tool, to evaluate how skin toxicity impacts QoL." (PMID 33973081, 2021). "According to the same study, the most common adverse events leading to withdrawal from EGFR-TKI treatment were related to skin toxicity." (PMID 32918131, 2021). "For the SNP rs534124757 of the EGFR gene it was shown that in patients carrying at least one A allel skin toxicity was less frequently." (PMID 34012511, 2021). "Only five patients received anti-EGFR agents, with two episodes of mild–moderate skin toxicity (40%)." (PMID 33513713, 2021).
skin toxicity (continued). "In a previous study, we demonstrated that EGF ointment is effective at managing EGFR inhibitor-related skin toxicities and improves patients’ QoL, compared with placebo, via a placebo-controlled, double-blind, multicenter, pilot phase III trial." (PMID 33113881, 2020). "Various types of medication used to treat EGFR inhibitor-induced skin toxicity were used, including antibiotics, steroids and moisturizers." (PMID 30557370, 2018). "If formally proven by replication, the SNPs associated with severe EGFR induced skin toxicity may be helpful to predict the occurrence and severity of skin toxicity in patients that will receive cetuximab and allow for adequate information on the risk of skin toxicity and prophylactic measurements." (PMID 30557370, 2018). "Until recently, the NCI CTCAE v 3.0 grading scale (published in 2006) had been used in most of the studies for evaluation of EGFR inhibitor induced skin toxicity." (PMID 29285233, 2017). "Further research is needed, using QoL tools specific for skin-related events, to assess the direct effect of skin toxicity on QoL for patients receiving EGFR inhibitors." (PMID 27083443, 2016). "The lack of a difference in QoL associated with different grades of skin toxicity suggests, however, that QoL tools specific for skin-related events are required to assess the direct effect of skin toxicity on QoL for patients receiving EGFR inhibitors." (PMID 27083443, 2016). "In ITT population, the main AEs of anti-EGFR agents are skin toxicity and the additional biotherapy were well tolerated." (PMID 23226426, 2012). "In spite of anti-EGFR-related skin toxicity, the overall HRQoL for patients receiving panitumumab+chemotherapy was not adversely affected." (PMID 21989186, 2011). "Osimertinib, another EGFR-TKI, was associated with skin toxicity in approximately 24% of patients." (PMID 41570298, 2026). "The reduction of skin toxicity and lower rate of discontinuation could increase long‐term treatment adherence in the EGFR‐sensitive patient population." (PMID 37269194, 2023). "In our prior study, we demonstrated that recombinant human epidermal growth factor (rhEGF) treatment is effective for managing epidermal growth factor receptor inhibitors (EGFRIs)-related skin toxicities and improves patients’ quality of life (QoL) compared with placebo." (PMID 33113881, 2020). "While there was no overlap with the GWA analysis on predictors for efficacy, it could well explain a relation with EGFR inhibitor induced skin toxicity since this type of toxicity is related to anti-tumor efficacy." (PMID 30557370, 2018). "Skin toxicity is a common AE related to epidermal growth factor receptor (EGFR) agents." (PMID 27541298, 2016). "Additionally, the severity of skin toxicity might be lessened if pre-emptive skin care interventions differ based on the studies and the patient administering anti-EGFR therapies." (PMID 36980549, 2023). "Although these adverse reactions are rarely serious or life-threatening, skin toxicity can significantly affect quality of life (QOL), causing both physical discomfort and psychological distress, which can affect compliance, thus affecting the efficacy of treatment with EGFR inhibitors." (PMID 32918131, 2021). "Even if considering only trials with similar settings (mCRC treated with EGFR inhibitors) the rates of grade ≥ 2 skin toxicity in the preemptive arms are considerably lower in previous studies with 20%, 21.3% and 29%) and could not be reproduced in the present trial." (PMID 29285233, 2017). "Regarding the onset time of EGFR inhibitor-related skin toxicity, early onset occurs in both Asians and non-Asians." (PMID 40888993, 2025). "The incidence of common adverse events, such as skin toxicity and liver dysfunction, did not increase with retreatment with EGFR-TKIs, and no new adverse events were observed." (PMID 40704256, 2025). "There is no recognized authoritative guide for the treatment of EGFR inhibitors related skin toxicity." (PMID 35223483, 2022).
skin toxicity (continued). "Building on the clinical promise of JDXZ granules for EGFR-TKI-induced skin toxicity demonstrated in this RCT, a follow-up RCT is warranted to rigorously assess the treatment’s efficacy and safety, with the goals of reducing skin toxicity and enhancing patient quality of life." (PMID 41570298, 2026). "In this study, skin toxicity did not predict the effectiveness of the anti-EGFR medication." (PMID 36980549, 2023). "The TCs benefit may be due to the development of patients’ skin toxicity and not due to the TC itself However, the effect of the concomitant use of EGFR-TKIs, PPIs, and TCs on the PFS and OS was similar to that of EGFR-TKI therapy alone." (PMID 36782147, 2023). "Indeed, not all patients that experience EGFR induced skin toxicity are responsive to EGFR inhibitor therapy and also not all responsive patients experience skin toxicity." (PMID 30557370, 2018). "However, since little was published about effective prevention of EGFR inhibitor-induced skin toxicity at time of the CAIRO2 study and this was not in the guidelines, it is highly unlikely that accurate prevention took place." (PMID 30557370, 2018). "Hypothesizing on relation of these genes to EGFR inhibitor-induced skin toxicity remains complicated, since the exact pathophysiology of EGFR inhibitor-induced skin toxicity is still not fully elucidated." (PMID 30557370, 2018). "Furthermore, despite the high incidence of skin toxicity, generic quality of life (QoL) instruments have shown no impact of EGFR inhibitors plus FOLFIRI on overall QoL." (PMID 27764839, 2016).
gastric adenocarcinoma (42 papers, 2008 to 2026). "GNAS encodes a G protein alpha stimulatory subunit and is of interest given activating mutations have been proposed to mediate resistance to EGFR inhibitors and activate Wnt/β-catenin signaling pathways in gastric adenocarcinomas." (PMID 32158697, 2020). "Epidermal growth factor receptor pathway genes significantly associated with risk of gastric adenocarcinoma overall and by anatomic sites*." (PMID 23874846, 2013). "Furthermore, EGFR inhibitors may provide an advantage in highly heterogeneous gastric adenocarcinomas by acting both on cells susceptible to the action on EGFR and cells sensitive to the off-target activity on ABCG2." (PMID 39033209, 2024). "Epidermal growth factor receptor (EGFR) is overexpressed in more than 30% of gastric adenocarcinoma (GAC) and esophageal adenocarcinoma (EAC) cases." (PMID 29228748, 2017). "The role of anti-epidermal growth factor receptor (EGFR) therapy is controversial in patients with esophago-gastric adenocarcinoma." (PMID 29228748, 2017). "Overexpression of EGFR protein has been reported in 24–27 % of all gastric adenocarcinomas and in 31 % of intestinal gastric adenocarcinomas." (PMID 27387915, 2016). "The expression of EGFR in the gastric adenocarcinoma cell strain SGC7901 was detected by RT-PCR and immunocytochemical analysis." (PMID 23833649, 2013). "Moreover, it has been reported that high expression of EGFR predicts poor survival in patients with resected T3 stage gastric adenocarcinoma." (PMID 38982548, 2024). "We performed this meta-analysis to evaluate whether the addition of an anti-EGFR agent to chemotherapy can produce survival benefits in patients with advanced esophageal adenocarcinoma, gastric adenocarcinoma, or gastroesophageal junction adenocarcinoma." (PMID 29228748, 2017). "ERBB2 amplification for anti-ERBB2 inhibitor treatment in breast and gastric adenocarcinomas, EGFR amplification for anti-EGFR inhibitors, MET amplification for MET tyrosine kinase inhibitors, and FGFR2 amplification for FGFR2 phosphorylation inhibitors have been reported as predictive markers." (PMID 23936009, 2013). "Therefore, our findings suggest that combining ABCG2 inhibitors or EGFR inhibitors with SN-38 or irinotecan could be a promising strategy in gastric adenocarcinoma." (PMID 39033209, 2024). "Interestingly, a PR was observed in a gastric adenocarcinoma patient with unknown EGFR and HER2 status." (PMID 24612546, 2014). "In a cohort of 950 patients with treatment-naïve gastric adenocarcinoma, 63.1% of tumors expressed at least one receptor tyrosine kinase (HER2, EGFR, MET, FGFR2), while 22.7% of these simultaneously expressed multiple biomarkers." (PMID 41303727, 2025). "Our study addresses this gap by screening pairwise pharmacological interactions of EGFR, mTOR, and c-MET inhibitors with chemotherapeutics from five distinct groups in gastric adenocarcinoma cells, rigorously inspecting the kinetics of cell death." (PMID 39033209, 2024). "Molecular targets, such as epidermal growth factor receptor (EGFR), mammalian target of rapamycin (mTOR), and c-MET, have shown significant involvement in the aggressiveness of gastric adenocarcinomas." (PMID 39033209, 2024). "We have shown that the upregulation of TWIST expression in gastric adenocarcinoma cells cultured in Hp-AGF secretome depended on EGFR detected at 96 h of experimental procedure and disappeared after the addition of EGFR inhibitor Tyrphostin A46." (PMID 37460910, 2023). "Results showed that this cotreatment modulated numerous critical proteins, such as EGFR/HER2/HER3, Kras/ERK/Vimentin, and mTOR/HIF1-α/HK2/LDHA pathways of gastric adenocarcinoma AGS cells." (PMID 36145507, 2022). "Of these, 8 regions contained previously characterized amplified oncogenes: GATA4, CCND1, CDK6, MDM2, EGFR, MCL1, ERBB3 and MYB; this is the first report of significant and nearly isolated MYB amplification in gastric adenocarcinoma." (PMID 28426752, 2017).
gastric adenocarcinoma (continued). "Tissue microarray analyzed that HER2, EGFR, MET and FGFR2 predominances were respectively observed in 10.1, 13.9, 16.1 and 22.9% of the gastric adenocarcinomas." (PMID 27738318, 2016). "Analogous to HER2 testing, determination of EGFR gene amplification status in concert with immunohistochemistry could improve the specificity of patient selection when investigating the possible benefits of anti-EGFR therapies in the treatment of gastric adenocarcinomas." (PMID 27387915, 2016). "There are several studies related to the expression and prognostic impact of EGFR and HER3 alterations in gastric adenocarcinoma." (PMID 26844548, 2016). "Two panels of combinatorial biomarkers, including EGFR, TTR, RANTES, and VN, are developed, which are less invasive method for the diagnosis of gastric adenocarcinoma." (PMID 22240791, 2012). "In conclusion, this meta-analysis indicates that the addition of an anti-EGFR agent to chemotherapy conveys no additional benefit for patients with advanced esophago-gastric adenocarcinoma." (PMID 29228748, 2017). "Thus, in gastric adenocarcinoma, VEGF-D expression levels may be of prognostic value, whereas the expression levels of the EGFR and TGF family may have only a minor effect." (PMID 25788990, 2015). "Lapatinib, a dual EGFR and HER2 receptor tyrosine kinase inhibitor, has also been investigated in metastatic esophago-gastric adenocarcinoma but without much success." (PMID 31772236, 2019). "One PR was observed in a gastric adenocarcinoma patient who failed 2 lines of chemotherapy and 1 VEGFR2 TKI; however, the tumor tissue from biopsy was not enough to assess EGFR and HER2 status." (PMID 24612546, 2014). "UWG02CTC also showed higher expression than UWG01CTC of targetable pathways including EGFR, FGFR2, HER-2 (ERBB2), and MET, as well as key genes in the JAK/STAT pathway, genes which overexpression are frequently reported in gastric adenocarcinomas but not gastrointestinal neuroendocrine cancers." (PMID 31953491, 2020).
HCMV infection (41 papers, 2011 to 2025). "This cell-type-dependent regulation of EGFR supports a possible requirement for EGFR signaling during CMV infection of CD34+ HPCs for the establishment of latency, and loss of EGFR or PI3K signaling enhances reactivation potential during infection." (PMID 30127257, 2018). "The steady state association of EGFR with Rab5 and Rab11 vesicles in the context of infection was surprising and indicates that HCMV infection has altered host trafficking." (PMID 27218650, 2016). "In addition, in the KEGG pathway enrichment analysis for the DEARGs, these genes were associated with EGFR tyrosine kinase inhibitor resistance, ERBB signaling pathway, and Human cytomegalovirus infection in Luminal BRCA." (PMID 32649310, 2020). "Epidermal growth factor receptor (EGFR) is an entry receptor for HCMV infection of CD34+ HPCs, and signaling through this pathway contributes to the establishment and maintenance of latency." (PMID 40736257, 2025). "The KEGG enrichment analysis suggested these drugs mainly work through multiple pathways in pathways in cancer, endocrine resistance, human cytomegalovirus infection, EGFR tyrosine kinase inhibitor resistance, proteoglycans in cancer." (PMID 40308779, 2025). "HCMV infection mediates the upregulation of Wilms’ tumor 1 (WT1) protein, a transcription factor associated with the negative regulation of EGFR." (PMID 38136637, 2023). "HCMV infection promotes the activation of EGFR signaling, which is required for entry into monocytes and stimulates cell movement." (PMID 38136637, 2023). "Activation of EGFR signaling by inducing HCMV gB-EGFR internalization is required for the translocation of viral DNA into the host nucleus and productive HCMV infection." (PMID 38136637, 2023). "In support of this cell type specific EGFR biology during HCMV infection, one can note the differences between EGFR-dependent signaling seen in infected monocytes vs. that seen in infected endothelial cells (ECs) or infected trophoblasts." (PMID 34025614, 2021). "EGFR signaling is also suggested to play a role in the establishment of latent HCMV infection in CD34+ HPCs by regulating several key early steps." (PMID 34299120, 2021). "In the context of latency, HCMV infection in CD34+ HPCs sustained a low basal level of EGFR activity." (PMID 34299120, 2021). "Following the engagement of heparan sulfate proteoglycans, HCMV infection of monocytes begins via the interaction of gB and the gH/gL complexes with host cell surface EGFR and β1 and β3 integrins." (PMID 34025614, 2021). "Rapid activation of the EGFR signaling pathway following HCMV infection also turns out to be essential for viral entry into monocytes." (PMID 34025614, 2021). "During human cytomegalovirus (HCMV) infection, epidermal growth factor receptor (EGFR), c-Raf, mitogen-activated protein kinases (MEK1/2), and extracellular signal-regulated kinases (ERK1/2) pathways were involved in COX2-mediated inflammation induced by HCMV." (PMID 34830477, 2021). "HCMV infection increases EGFR protein turnover, in addition to a transcriptional downregulation of EGFR, which together results in a 70% reduction in total levels of EGFR." (PMID 32630219, 2020). "It has been reported that HCMV infection and amplification are related to the expression of epidermal growth factor receptor (EGFR), platelet-derived growth factor receptor (PDGFR), and Toll-like receptors (TLRs), as well as integrin." (PMID 31370833, 2019). "EGFR or downstream PI3K signaling pathways inhibit replication in fibroblasts following viral entry, and HCMV infection results in the downregulation of EGFR early in infection." (PMID 30127257, 2018). "EGFR trafficking is required for translocation of the viral genome to the nucleus to initiate CMV infection, and inhibition of EGFR signaling shortly after entry significantly delays gene expression." (PMID 30127257, 2018).